ZNF780A (zinc finger protein 780A)
Description:
May be involved in transcriptional regulation.
Synonyms: ZNF780
Tractability: PROTAC: ubiquitination databases record sites on it.
Gene: Protein-coding gene on chromosome 19 (40,069,152 to 40,091,140, reverse strand). Ensembl gene ENSG00000197782.
Subcellular location: Nucleus
Subcellular location (Human Protein Atlas): Nucleoplasm; Centrosome
Gene Ontology:
Molecular function: protein binding; DNA-binding transcription factor activity, RNA polymerase II-specific; RNA polymerase II cis-regulatory region sequence-specific DNA binding
Biological process: regulation of transcription by RNA polymerase II; regulation of DNA-templated transcription
Cellular component: nucleus; nucleoplasm
Genetic constraint (gnomAD): Loss-of-function variants: 39 observed, 59.04 expected, observed/expected ratio (o/e) 0.66, 90% interval 0.51 to 0.86. The upper end of that interval is the gene's LOEUF score, 0.86, which puts it in group 3 of 6, group 1 being the genes least tolerant of losing a copy. Missense variants: 672 observed, 806.28 expected, observed/expected ratio (o/e) 0.83, 90% interval 0.78 to 0.89. Synonymous variants: 231 observed, 252.7 expected, observed/expected ratio (o/e) 0.91, 90% interval 0.82 to 1.02.
Homologues: Orthologues: chimpanzee ZNF780A (99% identical), mouse Zfp626 (59% identical), rat Zfp780b (59% identical), mouse Zfp607a (57% identical), mouse Zfp607b (56% identical), rat Zfp780b (55% identical), mouse Zfp850 (54% identical), mouse Zfp60 (54% identical), rat Zfp59 (52% identical), mouse Zfp59 (52% identical), rat LOC102553760 (51% identical). Paralogues in human: ZNF780B (87% identical), ZNF790 (41% identical), ZNF383 (41% identical), ZNF30 (40% identical), ZNF546 (39% identical), ZNF540 (39% identical), ZFP14 (38% identical), ZFP30 (37% identical), ZNF571 (37% identical), ZNF595 (36% identical), ZFP28 (36% identical), ZFP82 (36% identical), and 164 more.
Diseases named in the same sentence as ZNF780A in open-access papers:
ZNF780A is named in the same sentence as 3 diseases in open-access papers, as found by Europe PMC text mining. Sharing a sentence is not in itself a finding about the gene and the disease. The quoted sentences say what the papers report.
breast carcinoma (1 paper, 2020). "PE‐Lap (FBP1, ITGA11, TRIM68, BCAT1, ZNF780A, UTP20 and GRB7) predicted outcomes of breast cancer patients treated with lapatinib." (PMID 34766125, 2020).
ZNF780A also shares sentences with these, for which no sentence is quoted: autoimmune disease (1 paper); myopia (1).